LYZ (lysozyme)
Diseases named in the same sentence as LYZ in open-access papers (continued):
Sharing a sentence is not in itself a finding about the gene and the disease.
bacterial infection (107 papers, 2007 to 2025). "During bacterial infection, it translocates and polymerizes on bacterial surfaces to form pores, compromising bacterial envelope integrity and enhancing susceptibility to lysozyme-mediated degradation." (PMID 41007936, 2025). "Several lines of evidence suggested that the crustacea hemocytes, PO, and lysozyme activity play an important role in generating a protective immune response against bacterial diseases including those caused by vibrios." (PMID 35283820, 2022). "In other species, polymorphisms in lysozyme genes were also found to be associated with resistance to bacterial diseases." (PMID 24244553, 2013). "We propose that the engagement of host intestinal lysozyme with an enteric pathogen such as Salmonella promotes the release of barrier-impairing factors; therefore, elevated or abnormal lysozyme production is pro-inflammatory during pathogenic bacterial infection." (PMID 38823640, 2024). "The genes encoding lysozyme may have a function in the digestion of bacteria in food and are involved in intestinal pathogenic bacterial infection." (PMID 37918806, 2023). "Therefore, the deN PG backbone increases lysozyme resistance and thus participates in the heightened ability of the epidemic strains to evade host immune defenses and hence cause significant bacterial infections." (PMID 35545925, 2022). "IPNV infection causes lysozyme activity suppression, which may lead to secondary bacterial infections." (PMID 34359116, 2021). "For example, lysozyme produced by lytic bacteriophages hydrolyses peptidoglycan to favor the release of the viral progeny from the bacterial cell while animals produce lysozyme to protect themselves against pathogenic bacterial infection." (PMID 32411686, 2020). "On the other hand, Jaburetox does not enhance the antibacterial response, as unchanged hemolymph levels of lysozyme, cecropin and turbidimetric assays of bacterial growth were seen; and also as Jaburetox-treated insects were more susceptible to bacterial infection, indicative of immunosuppression." (PMID 27455853, 2016). "Coating medical implants and devices with lysozyme extracted from egg white is a potential strategy for preventing bacterial infections." (PMID 40807436, 2025). "Lysozyme is a key enzyme in fish innate immunity that helps protect against bacterial infections by breaking down bacterial cell walls." (PMID 41339441, 2025). "During bacterial infections, an increase in lysozyme activity is typically observed, as documented in infections caused by Y. ruckeri, among other pathogens." (PMID 41497472, 2025). "Lysozyme is a ubiquitous enzyme with excellent antimicrobial properties, which shields the eye against bacterial diseases." (PMID 39451696, 2024). "Further protection from bacterial infection occurs by the secretion of lysozyme, which was also easily detectable at the protein level in both the endocervical and the vaginal mucus." (PMID 38396964, 2024). "It has been shown that lysozyme activity increases after bacterial infections in fish, emphasizing its role in pathogen elimination (reviewed by Saurabh and Sahoo)." (PMID 39555512, 2024). "The intestinal mucus layer is composed of mucin, antibacterial peptide, and lysozyme secreted by goblet cells, which are essential for maintaining intestinal homeostasis and resisting intestinal bacterial infection." (PMID 38672341, 2024). "Changes in lysozyme level indicate the variation in tear composition or response to bacterial infections and inflammations." (PMID 39451696, 2024). "The innate defense mechanism of fish includes lysozyme, a hydrolytic enzyme that triggers the phagocytes and the complement system, leading to the lysis of bacterial infections." (PMID 38773537, 2024). "Innate immune molecules, including antimicrobial peptides (for example, defensins) and lysozyme, function to delay or prevent bacterial infections." (PMID 36598227, 2023).
bacterial infection (continued). "AMPs and lysozyme are produced within hours in the fat body and hemocytes upon bacterial infection and secreted into the hemolymph to eliminate invading pathogens." (PMID 37958748, 2023). "Lysozyme is considered to be one of the important anti-bacterial molecules in fish since it plays a vital role in host responses against bacterial infections." (PMID 36551460, 2022). "Lysozyme, an enzyme derived from avian egg white, aids in nutrient digestion and absorption and provides protection against bacterial diseases while lowering pollutants’ excretion, such as ammonia." (PMID 35405887, 2022). "In another study, similar results were shown for pacu, Piaractus mesopotamicus fed with β-glucan, where the respiratory burst activity and lysozyme activity were higher after A. hydrophila infection than before the bacterial infection." (PMID 36138767, 2022). "In fish, the antimicrobial activity of complement factor C3, lysozyme, and cathepsins B and L in the mucus increases after bacterial infection." (PMID 36419596, 2022). "Lysozyme is an important enzyme for our defense against bacterial infections, by its cleavage activity against a bond between two sugar units in the bacterial cell wall, and thereby an important component of innate immunity." (PMID 36430453, 2022). "LYZ has been shown to play an important role in shrimp resistance to viral and bacterial infections." (PMID 36189245, 2022). "We also report that fructose mainly enhances the expression of lysozyme and C3, which enable the bacteria to be reduced more efficiently, thus highlighting a metabolism-based approach to combat bacterial infection in aquaculture." (PMID 35386717, 2022). "The lysozyme Cclys2 is an effective immune effector in the immune response of C. chinensis and can be stimulated by bacterial infection." (PMID 33920041, 2021). "The effect of lysozyme (from chicken egg white and rhLys) on E. faecalis biofilm was studied in a 2019 patent and a kit with lysozyme was developed for treating such a bacterial infection." (PMID 34943746, 2021). "Eicosanoids mediate immune reactions to bacterial infections in tobacco hornworms Manduca sexta and modulate expression of antimicrobial peptides (AMPs) such as lysozyme and cecropin in Bombyx mori." (PMID 35069239, 2021). "After the bacterial infection, only lysozyme and mpo genes were affected by the type of β-glucan with an increase of their expression with Gas1 in comparison with MG diet (p < 0.05)." (PMID 34295335, 2021). "Recently, a Chinese patent reported the identification of a bacteriophage lysozyme and its gene, as well as its use for preventing and treating bacterial infections." (PMID 34943746, 2021). "Along with phenoloxidase and lysozyme enzymes, AMPs perform a key role in humoral defense against bacterial infection." (PMID 32231138, 2020). "The T7 lysozyme and T7 RNA polymerase complex stimulates phage gene expression during host bacterial infection." (PMID 32708328, 2020). "Lysozyme can be found on the body surface, skin, serum, gills, and intestinal tract of teleost species and is considered as a protective factor against bacterial infection due to its antibacterial proprieties." (PMID 32231137, 2020). "The antibacterial lysozyme activity observed here represents a defense mechanism against bacterial infections for M. infundibulum." (PMID 31284386, 2019). "Lysozyme is an important innate immunity factor that kill bacteria, thereby preventing bacterial infection, and commonly exists in the coelomocyte and coelomic fluid of echinoderms." (PMID 29719735, 2018). "Paneth cells within the base of murine and human intestinal crypts release antimicrobial products such as lysozyme which help to prevent bacterial translocation across the gut epithelium to protect the crypts from bacterial infection." (PMID 29970174, 2018).
bacterial infection (continued). "In conclusion, the data in this study demonstrate that human lysozyme is beneficial for the gut performance of neonatal piglets and improves resistance to bacterial infections, providing an effective preventive measure for diarrhea." (PMID 29463305, 2018). "In the process of anti-bacterial infection, lysozyme often used as an important indicator that reflects strength of non-specific immunity." (PMID 27582731, 2016). "The work reported here is an initial step in breeding pigs for diarrhea resistance by specifically expressing human lysozyme in mammary gland tissue to benefit piglet health and improve their ability to resist bacterial infections." (PMID 24586544, 2014). "Lysozyme is an essential component of the host innate immune system which fights bacterial infection by cleaving cell wall saccharides and σV induces resistance to lysozyme." (PMID 25275625, 2014). "Lysozyme activity is usually more related to bacterial infection and PO activity to fungal and multicellular hemolymph-invading organisms." (PMID 18154650, 2007). "Elevated levels of LYZ and NO, which are primarily produced by phagocytic cells, may indicate a response to bacterial infection and serve as critical markers of inflammation." (PMID 41383965, 2025). "Additionally, RNA-seq analyses of Aedes aegypti and Anopheles gambiae under microbial induction revealed that bacterial infection responses primarily involve an upregulated expression of defensins and lysozyme." (PMID 40429662, 2025). "Secretory autophagy redirects LYZ during bacterial infection." (PMID 40416362, 2025). "Amongst the proteins identified during proteomic analysis that were decreased in CepEVs were DEFA3, LYZ, CAMP, LTF, and BPIFB1, all of which had strong associations with defense response to bacterium (GO: 0042742), as well as the immune response to bacterial infection." (PMID 41550953, 2025). "The basic attention is devoted to the immune-modulating activity of TDNG following exposure to the bacterial infection (P. putida) which is indicated by augmenting levels of C3 and LYZ plus up-regulation of the response of the BCL-2 and down-regulation of caspase-3." (PMID 38561720, 2024). "Likewise, elevated lysozyme activity (LYZ), the expression of immune-related genes (e.g., il-1β, tnf-α), and the modulation of resistance to pathogenic bacterial infection from Yersinia rukeri (Pseudomonas fluorescens) were also reported." (PMID 38136186, 2023). "Among the upregulated genes that are associated with SARS‐CoV‐2 infection, 15 were related to adaptive immunity, innate immunity (LYZ, coding for lysozyme), interferon response, and bacterial infection, which was particularly noticeable in the PBMCs of Proto‐infected animal." (PMID 38020713, 2023). "Insects can also resist bacterial infection through lysozyme shear activity." (PMID 35935997, 2022). "Many studies have demonstrated that the Toll and IMD signaling pathways can inhibit viral and bacterial infections by regulating the expression of AMPs (such as crustin, penaeidin, anti-lipopolysaccharide (anti-LPS) factor, and lysozyme, promoting apoptosis and producing ROS." (PMID 35116034, 2021). "Lysozyme has important roles in tear fluids to protect the eye from bacterial infection." (PMID 34316222, 2021). "Therefore, when H. illucens larvae experience a limited bacterial infection, phagocytosis, antimicrobial peptide production, and lysozyme activity are sufficient to counteract the threat, inhibiting at the same time the activation of the PO system." (PMID 34867970, 2021). "It was suggested that the up-regulation of the c-type lysozyme (lysC) in the skin of common carp exposed to KHV could be a response of secondary bacterial infection." (PMID 33187217, 2020). "Many studies have reported elevated levels of lysozyme expression following bacterial infection." (PMID 32082185, 2019).
bacterial infection (continued). "Finally, considering that controlling bacterial infections is currently one of the main problems of aquaculture on an industrial scale, lysozyme is attracting the interest of researchers for its potential applications in aquaculture." (PMID 30597935, 2018). "Thus, real-time monitoring of lysozyme concentration in a human body can pave a facile route for early warning for potential bacterial infections." (PMID 29662878, 2018). "Therefore, the horizontally acquired lysozyme genes are likely to be acting to augment bivalves’ capacity to restrict bacterial infections." (PMID 28100665, 2017). "While pathogenic species such as S. aureus are completely resistant to lysozyme, S. carnosus and other non-pathogenic species are sensitive to lysozyme, which is produced by mammalians in response to a bacterial infection." (PMID 28971248, 2017). "Therefore, an increasing amount of research has focused on the use of natural antibacterial proteins, such as lysozyme, as an antibiotic-free approach to treat bacterial infections." (PMID 24586544, 2014). "In holometabolous insects, up-regulated immune functions including lysozyme production have been detected in the midgut of mature larvae before pupation, which are presumably vulnerable to bacterial infections during the radical developmental reorganization of metamorphosis." (PMID 23691247, 2013). "Interestingly, a lysozyme has also been reported to be upregulated during larval metamorphosis in M. sexta, and has been proposed to provide protection from bacterial infection." (PMID 17588272, 2007). "Consequently, preparations from inoculated hives may exhibit superior therapeutic potential due to their higher lysozyme content, enhancing the overall efficacy of the formulation in combating viral and bacterial infections." (PMID 41306594, 2025). "Interestingly, both SeNP and Trolox offered similar magnitudes of protective effects the A. hydrophilla challenge, suggesting that the increase in lysozyme activity alone may be sufficient to counter bacterial infection." (PMID 35624828, 2022). "Therefore, lysozyme may have been systemically activated in response to bacterial infection in grouper, with its expression not limited to the liver." (PMID 31836758, 2019). "The existence of multiple intracellular cod g-type lysozymes with no or very low enzyme activities, and the demonstrated modulation of lysozyme gene expression by bacterial infection and IFNγ, allows speculations about a possible role for lysozymes in the process of selective autophagy of bacteria." (PMID 27324690, 2016). "Considering the similar expression patterns of lysozyme gene and defensin-like gene, we suggest the possibility that the lysozyme and defensin-like gene product may be involved in suppression of improper bacterial infections in the midgut." (PMID 23691247, 2013). "LYZ and ALP are critical innate immune factors capable of killing bacteria and impeding bacterial infections." (PMID 40867787, 2025). "Moreover, SP supplementation alone or mixed with Bacillus licheniformis enhanced the transcriptional levels of Lysozyme, Il-6, Il-1β, Tgf, and TNF-α, which in turn increased the goldfish resistance to bacterial infection and lowered its mortality rate." (PMID 39453066, 2024). "The enzyme LYZ, which is secreted by fish white blood cells and acts as an antibacterial, contributes to preventing bacterial infection, and that considered one of the most active non-specific immune response tools." (PMID 39026256, 2024). "These structures are critical components of a functional airway as they participate in the innate immune system by secreting lysozyme and mucus, and an absence of SMGs in the tracheas results in increased bacterial infection." (PMID 37508804, 2023). "The ability of fish to compete with the bacterial infection is determined by evaluating their levels of lysozyme, a key non-specific defense molecule of the immune system." (PMID 37889734, 2023).
bacterial infection (continued). "In the current study, the activity of lysozyme, nitric oxide, and complement 3 and the globulin level experienced higher values in AVP-incorporated diets, suggesting an immune-modulating impact of AVP and an increased tolerance of the bacterial infection." (PMID 36009213, 2022). "Lysozyme can hydrolyze bacterial cell walls and operates as a non-specific innate defense molecule against bacterial infections." (PMID 35812341, 2022). "None of the probands had bacterial infections as indicated by the low plasma lysozyme concentrations." (PMID 33393613, 2021). "Conversely, genes up-regulated in aposymbiotic relative to symbiotic individuals, including a chicken-type lysozyme gene and a defensin-like protein gene, are possibly involved in regulation of non-symbiotic bacterial infections." (PMID 23691247, 2013). "Finally, both lysozyme genes (INF-152 and INF-282) are induced after sterile injury, independently of the bacterial infection." (PMID 18925938, 2008). "Moreover, despite bacterial infections inducing the activation of lysozyme in that aphid, this enzyme does not seem to have a direct role in the host immune response against bacteria." (PMID 34867970, 2021). "In the present experiment, the results might indicate that the stimulation of ACH50 and lysozyme activities, Ig and monocyte production was not in itself sufficient in this case to protect the fish against bacterial infection." (PMID 34295335, 2021). "Similar to lysozyme, which was shown to deliver PGN fragments to the cytoplasmic PGN receptor NOD2, the Arabidopsis lysozyme-like activity LYS1 produces PGN-breakdown products with immunogenic activity, and lys1 mutant plants are compromised in their resistance to bacterial infection." (PMID 26679352, 2015). "Additionally, the humoral response, monitored by the prophenoloxidase system activation and the lysozyme activity, confirmed that the larvae’s immune system was not significantly stimulated by the injected nanosystem, irrespective of the presence of bacterial infection." (PMID 39590485, 2024).